CD4 (CD4 molecule)
Diseases named in the same sentence as CD4 in open-access papers (continued):
Sharing a sentence is not in itself a finding about the gene and the disease.
tumor (continued). "Contrastingly, when HPV− tumor cells interacted with CD4+T cells, such a specialized subcluster remained elusive." (PMID 39105803, 2024). "We also confirmed the induction of high levels of MHC-II and PD-L1 on the EpCAM+ tumor epithelial cells co-cultured with IEL CD4 or CD3+ T cells." (PMID 38327516, 2024). "NAPSL.p@OVA vaccination effectively reduced regulatory T cells (Tregs, CD3+CD4+ Foxp3+ T cells) and myeloid-derived suppressor cells (MDSCs, CD11b+Gr-1+) in tumor tissues." (PMID 38764014, 2024). "CD4+ T cells have the ability to kill tumor cells directly and cytolytically, as well as create cytokines like IFNγ that strengthen the immune system’s ability to fight cancer." (PMID 39712007, 2024). "The CD4+ T cells are revealed to be able to kill autologous tumour cells in a MHC class II‐dependent manner." (PMID 38652109, 2024). "Tumor-specific CD4+ T cells play a crucial role in the immune response against cancers, promoting the activation of cytotoxic CD8+ T cells to increase their ability to destroy tumors." (PMID 39669558, 2024). "The subsequent single-cell and spatial analysis led to the discovery of cellular triads of CXCL13+ CD4+ T cells, DCs with maturation and regulatory molecules, and tumour-specific progenitor exhausted CD8+ T cells in the tumour of responders." (PMID 38760445, 2024). "Many anticancer therapies have been shown to induce tumor cell senescence, which promotes the recruitment and activation of CD4+ and CD8+ lymphocytes and enhances antitumor protection." (PMID 38504990, 2024). "Naïve T-helper lymphocytes (CD45RA CD4+) were also enriched in the R subgroup consistent with a constitutive anti-tumour host immune response." (PMID 39168966, 2024). "In marked contrast, the degree of tumor-infiltrating T cells positive for CD4, CD8, and CD45RO were significantly lower in the tumors with prognostic bacteria than their counterparts (P = 0.005, P = 0.03, and P = 0.005, respectively)." (PMID 38242997, 2024). "We also analyzed the intratumoral infiltration of regulatory T cells (Tregs, CD3+CD4+ Foxp3+), given Tregs’ role in restraining anti-tumor immune responses of CTLs." (PMID 39613774, 2024). "Of these, CD4+ Th1 cell can promote the effective antitumor-immunity and induce more durable immune-mediated tumor control than CD8+ T cell." (PMID 38662077, 2024). "Patients in the low Cov-2S group exhibited marked upregulation of various processes, including priming, activation, recruitment of CD4 T cells, and infiltration of immune cells into the tumor." (PMID 38601163, 2024). "In HNSCC, the TME is composed of tumor-infiltrating immune cells such as CD4+ and CD8+ T cells, myeloid-derived suppressor cells, and tumor-associated M1- or M2-polarized macrophages (TAMs) that interact with tumor cells to promote or suppress growth." (PMID 39630300, 2024). "As a prominent subpopulation of tumor-infiltrating CD4+ T cells, Tregs suppress anti-tumor responses and indicate a potential clinical target for tumor immunotherapy." (PMID 38167862, 2024). "In the spleen of 4T1 tumor-bearing mice, the numbers/percentages of the lymphocytic subpopulations CD4+ and CD8α+ T-cells, B-cells, NK and NK-T cells significantly increased in response to chitin + anti-PD-1 combination treatment." (PMID 38605414, 2024). "It is worth noting that this phenomenon of naive cells accumulating in the tumor‐normal interface not only occurs in CD4+ and CD8+T cells but also in B cells." (PMID 39716897, 2024). "Given the unique ability of cDC1 to cross-present tumor antigens to CD8 T cells as well as their ability to engage CD4 T cells, they are regarded as the primary DC subset that orchestrates antitumor T cell responses." (PMID 38903502, 2024). "First, cryoablation of the primary tumor not only upregulates the expression of PD-L1, but also facilitates the infiltration of CD8+ T cells and increases the expression of PD-1 on the surfaces of CD8+ T cells and CD4+ T cells within the secondary tumor." (PMID 39489086, 2024).
tumor (continued). "Consistently, a previous study demonstrated that the activated CD4+ T cell subset in the peripheral blood was a potent mediator of anti-tumor immunity." (PMID 38650951, 2024). "Our cellular network analysis via CellPhoneDB highlights a robust cell–cell interaction between HPV+ tumor cells and CD4+T cells." (PMID 39105803, 2024). "To confirm the differences found in mRNA markers for T‐cell infiltration in tumors between Panx1 genotypes, we performed IF staining on PLP‐fixed tumor cryosections to verify the presence of CD4+, CD8+, and Foxp3+ lymphocytic cells." (PMID 38327091, 2024). "Mature MDSCs can induce the differentiation of CD4+ Th1 cells to maintain durable anti-tumor immunity." (PMID 38791188, 2024). "The presence of CD4+ T and CD8+ T cells within the tumor exhibited a positive association with the presence of CD8+ T cells, while demonstrating a negative association with the presence of regulatory T cells (%Treg) within the tumor." (PMID 38730579, 2024). "Specifically, it was discovered that these receptors are required for the tumor suppression that the CD4+ T cell-microglia circuit mediates." (PMID 38391974, 2024). "Treatment with OV-mOX40L reduced tumor growth, increased iCAF levels, decreased myCAF levels, reinvigorated intratumoral immune cells, activated CD4+ and CD8+ T cells, and reduced Tregs." (PMID 39845957, 2024). "The presence of these immune cells within the TME, particularly naive B cells and resting CD4+ memory T cells, profoundly influences tumor growth and metastasis, potentially indicating an immune response associated with immune evasion." (PMID 39896800, 2024). "The infiltration of NK cells, eosinophils, macrophages, and CD4+ T lymphocytes in tumors plays a crucial role in regulating tumor metastasis." (PMID 39735532, 2024). "When data from the treatments were compared based on distance from the interface, we saw an improvement in CD4+/CD8+ T-cell penetration into the tumor in TGFβ and Cox2 siRNA treated sample." (PMID 38204925, 2024). "This increase in tumor-infiltrating ILC2s is accompanied by a dampened immune response mediated by CD4+ T/CD8+ T cells." (PMID 38430390, 2024). "Tumor neoantigens are capable of being recognized by CD8 and CD4 T cells within the tumor environment, thereby eliciting an antitumor immune response in vivo." (PMID 39329742, 2024). "In the tumor, we also found greater PD-1 expression in CD4+, CD8+, neoplastic, and Tregs in SS tumors." (PMID 38670099, 2024). "It has been demonstrated that NETs promote T Reg differentiation via the metabolic reprogramming of naïve CD4+ T-cells, promoting tumor development by suppressing cancer immunosurveillance." (PMID 38612483, 2024). "Enhancing the antigen-presenting cell MHC class II-restricted tumor antigen presentation to CD4+ T cells is a critical issue for triggering protective immunity and re-orienting the TME toward an antitumor state." (PMID 38994929, 2024). "In the MCa-M3C mouse model, increased CD8+ T cell and DC (Gr-1+CD11c+) numbers and decreased Treg cell numbers (CD4+FOXP3+) in tumor tissues, and increased CD8+ T cell numbers in spleens were found in IR + DSF/Cu-treated mice." (PMID 38678042, 2024). "LvM suppress systemic anti-tumor immunity which likely reduces tTreg differentiation from CD4-single positive (CD4-SP+) thymocytes reducing T-regs in peripheral blood circulation." (PMID 38643348, 2024). "In this study, we investigated the potential of tumor-derived exosomes to modulate CD4+ T cells function, potentially compromising antitumor immunity." (PMID 39079960, 2024). "A similar report pointed out that PLA2G2D positively correlated with CD8+T cells, M1 macrophages and CD4+ memory activated T cells and negatively correlated with M2 macrophages, suggesting its potential anti-tumor effect." (PMID 39239507, 2024).
tumor (continued). "The outcomes demonstrated that the Apilimod + LNP@PTEN group attained the highest CD8+/CD4+ ratio, implying a more robust anti-tumor immune response relative to the other treatment groups." (PMID 38898927, 2024). "In functional assays, we demonstrated that targeting Ripk4 in a murine lung metastatic TNBC model significantly reduced tumor burden, improved survival, and increased CD4+ and CD8+ T cell infiltration." (PMID 38744952, 2024). "In conclusion, TAMs promote tumorigenesis by interacting with CD4+ T cells, while CD4+T cells in turn act on TAMs to further enhance tumor immune escape." (PMID 38957393, 2024). "Significant correlations between PD-L1+ lymphocytes and tumour-infiltrating CD4+, Foxp3+CD4+, IL-17A+CD4+ T cells and M2 macrophages were found." (PMID 39409156, 2024). "Antigen peptides from tumor cells are generally presented to CD4+ T cells via MHC II on dendritic cells (DCs)." (PMID 38646639, 2024). "At the invasive margin, high expression of CD3, CD4, CD8, and CD45RO, along with CD4 and FOXP3, at the tumor center was associated with improved overall survival." (PMID 38787209, 2024). "The proximity analysis revealed that the CD8+ T cells in this spatial architecture were significantly closer to themselves and the CD4+ T cells than to the tumor cells." (PMID 38611111, 2024). "In patients with MIBC enriched with CD19 + B cells, these cells can act as antigen presenting cells to activate CD4 + TIT cells in the tumor environment of MIBC." (PMID 38216927, 2024). "ICIs target the dysfunctional immune system and stimulate the anti-tumor activities of lymphocytes, particularly the CD4+ and CD8+ T cells, to suppress tumor growth." (PMID 38673829, 2024). "In CTCL, a sequence mutation in pro-IL-16 reduces p27KIP1 levels, enhancing cell proliferation; in MM, overexpression of secreted IL-16 induces plasma cell proliferation; and in breast cancer, increased IL-16 recruits CD4+ pro-tumor macrophages." (PMID 39408600, 2024). "The findings from both univariate and multivariate survival studies demonstrated that the presence of tumor-infiltrating CD4+ T cells, CD8+ T cells, and the percentage of M1 macrophages were individually associated with the prognosis of OS and DFS." (PMID 38730579, 2024). "Using TCR sequences to link clonally related T cells, we identified 7,183 CD8+ T cells (17.8% of total CD8+) and 145 CD4+ T cells (0.71 % of total CD4+) in the blood which were clonally related to predicted-reactive T cells in the tumor." (PMID 38464315, 2024). "Recent reports underscore the multiple functions and diverse roles of CD4+ T cells in promoting tumor rejection in vivo." (PMID 39292790, 2024). "We selected tumor-infiltrating immune cell populations and defined them according to classical markers or evidence from the literature, including NK cells, CD4+ T cells, CD8+ T cells, myeloid cells, and B cells." (PMID 38622125, 2024). "CD4+ T cell depletion led to increased tumor growth in the control group, supporting the essential role of CD4+ T cells in controlling tumor progression." (PMID 38518770, 2024). "In both B16-F10 and CT26LacZ tumors, 49 and 42% CD4+ resident T cells expressed PD-1, respectively, which increased to 58% in both tumor types following treatment with NDV." (PMID 38328418, 2024). "SIGLEC9 upregulation was observed in tumor-infiltrating lymphocytes (TILs), including CD4+ and CD8+ T cells in colorectal cancer (CRC)." (PMID 39727942, 2024). "It resulted in increased mice survival through elimination of the CD4 + PD1high Tfh cells and associated GC B cells and interestingly by reactivation of cytotoxic CD8 T cells in the tumor microenvironment." (PMID 38321568, 2024). "The ratio of tumor cells versus total splenocytes, CD4+ and CD8+ T cells was 1:50, 1:15, and 1:10 respectively, to mimic the relative proportion of the various lymphocyte subpopulations of the spleen." (PMID 39035008, 2024).
tumor (continued). "Further expand the scope, bacterial immunotherapy for cancer also induces CD4-dependent tumor-specific immunity through tumor-intrinsic γ-IFN signaling." (PMID 38630135, 2024). "TILs primarily consist of anti-tumor cells, including CD8+ and CD4+ T cells (helper T cells), with CD8+ T cells associated with a good prognosis." (PMID 39458936, 2024). "CD4+ T cells secrete different tumouricidal cytokines, such as interferon-γ (IFNγ) and TNFα to support CTLs in the disruption of primary tumour cells." (PMID 39000359, 2024). "A potential shortcoming of pVACtools as used in this trial is the emphasis on MHC class I binding given the importance of CD4 cells in reprogramming the tumor microenvironment and promoting antitumor immunity." (PMID 39538331, 2024). "Mature B cells can generate tumor-specific antibodies and promote T-cell activation via the presentation of tumor antigens to CD4+ T cells." (PMID 38653982, 2024). "A significant association between PD-L1 expression subgroup and the number of tumour-infiltrating CD4+ T cells, Foxp3+CD4+ T cells, and M2 macrophages was found." (PMID 38541208, 2024). "Icariside I's immunological anti-tumor efficacy was further reinforced by a notable increase in a number of lymphocytes, involving CD4+ T, CD8+ T, NK, and NKT cells, demonstrating an improvement in host immune function." (PMID 39567970, 2024). "It has been shown that female tumor patients have higher serum and CD4+ T-cell membrane levels of PD-1 than males." (PMID 38254871, 2024). "Activated & resting Treg %CD4 + cell was positively associated with the risks of CRC, while DN (CD4-CD8-) %leukocyte cell exhibited a protective role in tumor progression." (PMID 38902711, 2024). "After activation, CD4+ T cells differentiate into Th1-type cells producing high levels of Th1 cytokines, which has been shown to be a major mediator in tumor control." (PMID 38920557, 2024). "The tumor infiltrating DCs, CD4+T and CD8+T cells were substantially increased after HLJD and ICIs co-treatment." (PMID 38605368, 2024). "Another DC vaccine with MHC-II binding HER3 peptide exhibits anti-HER3 CD4+ Th1 immune response to inhibit tumor growth in HER3 overexpressing in vivo breast cancer murine model." (PMID 38715072, 2024). "Administration of SGLT2 inhibitors as monotherapies suppressed tumour cell growth while simultaneously promoting CD4+ and CD8+ T-lymphocyte infiltration." (PMID 39403376, 2024). "Note that in 4T1 and B16F10 tumor models, the relative abundance of FoxP3+ cells is higher than that of CD4+ and CD3ε+ cells in most runs." (PMID 38605049, 2024). "FC analysis of the tumor-infiltrating immune cells of these micerevealed profound increases in DCs, macrophage, and CD4+ and CD8+ T cell abundance." (PMID 39051165, 2024). "Natural killer (NK) cells and CD4 T cells support the efficient activation of CD8 T cells but exhibit dysfunctional phenotypes in tumor microenvironments and in chronic viral infections." (PMID 38788198, 2024). "In patients undergoing tumor resection, CD4+ and CD8+ TILs increased in patients with neoadjuvant FOLFIRINOX compared to those with upfront surgery." (PMID 39249118, 2024). "Host MPO deficiency significantly reduced both CD11b+Ly6G+ myeloid cells, macrophages (CD11b+F4/80+) and exhausted CD4+PD1+CTLA4+ T cells within the tumor microenvironment." (PMID 38367056, 2024). "In tumor tissues, CD4 and CD8 T cell markers (present in TSE-positive; nearly absent in TSE-negative samples) showed an inverse relationship with PDPN expression (nearly absent in TSE-positive; present in TSE-negative samples)." (PMID 38355607, 2024). "In contrast, CD11c:DTA mice had a higher proportion of CD4+CD44+CD62L− T cells in tumor tissues than WT mice." (PMID 39206204, 2024). "Antitumor immunity of B cells is mainly achieved by producing tumor antigen-specific immunoglobulins, presenting antigens to CD4+ T cells, and driving CTL activation and cytotoxicity." (PMID 38538718, 2024).
tumor (continued). "The overexpression of the marker gene RGS-5 and IL-6 stimulation of tumor-derived pericytes mediate CD4+ T-cell anergy in vitro, elicited by the upregulation of anergy-related factors (dgkα, erg2, and erg3)." (PMID 39086395, 2024). "Studies have demonstrated that exosomes derived from tumor cells, CD4 T cells, DC cells, NK cells, macrophages (M1), and CAR‐T cells can directly or indirectly improve the immune response." (PMID 39015555, 2024). "B-cells form antigen-specific immune responses in the tumor microenvironment by presenting antigens to CD4+ and CD8+ T-cells." (PMID 38159260, 2024). "Though GABA is generally recognized as a neurotransmitter, the molecule exhibits multiple bioactivities including the regulation of immune cells such as CD4+ and CD8+ T cells, tumor-associated macrophages, etc." (PMID 38637808, 2024). "CD4+ T lymphocytes can be manipulated by tumor cells to promote tumor development and metastasis, making them a prognostic factor in various types of cancer." (PMID 38690280, 2024). "CTLA-4 (CD152) is predominantly expressed on the surface of activated T cells as well as in regulatory T cells (Tregs) and PD-1+ CD4+/CD8+ tumor-infiltrating lymphocytes (TILs)." (PMID 38627681, 2024). "Previous studies have shown that PNI is significantly correlated with tumor infiltrating lymphocyte status, the density of CD4 + and CD8 + immune cells, and systemic inflammation." (PMID 38267897, 2024). "Given the increase in pro-inflammatory CD4(+) T cells after oHSV treatment, we next analyzed IFN-γ, TNF-α, IL-4, IL-17A, and IL-21 intracellular expression within the CD4(+) tumor infiltrates." (PMID 38895115, 2024). "CD8+ T cell depletion completely abrogated the inhibition of tumor growth in C5aR−/− mice, whereas CD4+ T cells had a partial effect, indicating that the enhanced antitumor immunity depends on CD8+ T cells." (PMID 38098230, 2024). "We found that Neo-CT–treated patients displayed an elevated infiltration of CD4+ T cells into the central tumor tissues and a tendency for a more dominate peritumoral localization of CD8+ T cells." (PMID 38335302, 2024). "Of note, the effect of anti-CD8 antibodies on tumor growth was more profound than anti-CD4 antibody." (PMID 39256398, 2024). "LAG-3 is expressed on the cell membranes of tumor-infiltrating lymphocytes (TILs), activated CD4+ and CD8+ T cells, and regulatory T cells (Tregs), where it binds to MHC-II molecules on antigen-presenting cells." (PMID 39743998, 2024). "The immunological changes induced by A. muciniphila and E. hirae in mice included the promotion of IL-12 secretion by dendritic cells and the accumulation of CCR9+ CXCR3+ CD4+ T cells in the tumour microenvironment." (PMID 39634265, 2024). "To test, in this study, a subcutaneous B16F10 tumor model was established, and IFNγ, the effector cytokine of CD4+ Th1 cells, was in vivo neutralized post cryo-thermal therapy with a monoclonal antibody (mAb)." (PMID 38827732, 2024). "The combination of these three agents induced an immune-infiltrated tumor microenvironment with increased CD4+ and CD8+ T cells, and decreased TAMs and Treg cells, leading to improvement in the response of KP tumors to checkpoint inhibitors." (PMID 38734764, 2024). "Macrophage depletion with clodronate reduced the tumor-infiltrating effector CD4 and CD8 T cells, impairing their antitumor functions." (PMID 38517331, 2024). "Ex vivo tumor cultures and patient-derived xenograft models demonstrated that human IL-7 upregulated pro-inflammatory cytokines and activated infiltrating CD4+ and CD8+ T cells in a dose-dependent manner." (PMID 38424167, 2024). "In this study, the injection of galectin 7 reduced CD4+ T cells and suppressed tumor growth in the MC38 syngeneic mouse tumor model using WT mice but not in PD-1 KO mice." (PMID 38503797, 2024).